ERBB2 (erb-b2 receptor tyrosine kinase 2)
Diseases named in the same sentence as ERBB2 in open-access papers (continued):
Sharing a sentence is not in itself a finding about the gene and the disease.
breast cancer (continued). "Amplification of the ERBB2 gene was found in 20% of breast cancer cases and a mutated version of the epidermal growth factor receptor (EGFR) gene in 30% of glioblastomas." (PMID 33806009, 2021). "Several ERBB2 mutation-targeting therapies have been proven to be effective for breast cancer patients." (PMID 33893247, 2021). "Amplification and overexpression of ERBB2 encoding the human epidermal growth factor receptor 2 (HER2) distinguishes a subtype of breast cancers that accounts for approximately one-fifth of all invasive breast cancer cases." (PMID 33886505, 2021). "Germline variants of ERBB2 have been associated with hereditary lung carcinoma and identified as a potential risk factor for breast cancer and melanoma." (PMID 34209587, 2021). "Overexpression of HER2 or amplification of the encoding gene, ERBB2, defines a subset of breast cancer typically representing 15–20% of all cases." (PMID 34136934, 2021). "ErbB2 is overexpressed in approximately 25% of human breast cancers, associated with clinically aggressive disease." (PMID 33946495, 2021). "Previous studies have shown that the co-amplification of CCNE1 and ERBB2 is associated with trastuzumab resistance in breast cancer and GC64,76." (PMID 34168152, 2021). "In fact, overexpression of ERBB2 was shown to facilitate invasion and metastasis of breast cancer and to associate with low overall survival." (PMID 34307654, 2021). "Molecular targets such as estrogen receptor (ESR1) and human epidermal growth factor receptor 2 (ERBB2) play an important role in breast cancer management and have also been associated with urothelial bladder cancer." (PMID 34073233, 2021). "Up-regulation of BCAR4 (the CA153 susceptibility gene) in the human breast cancer ZR-75-1 cell line promotes the phosphorylation of ERBB2 and ERBB3, enhances the estrogen-dependent effect of tumor cells, and stimulates the proliferation of tumor cells." (PMID 34630106, 2021). "Trastuzumab was the first ErbB2-targeting drug to be used in HER + breast cancer, therefore, trastuzumab-associated cardiotoxicity is the most well-studied cardiotoxicity of the cardiotoxicities associated with Erb2-targeting drugs." (PMID 34790121, 2021). "The gene expression profile of breast cancer-associated genes is different in Rlip+/− and Rlip−/− PyVT and Erbb2 mouse tumors relative to Rlip+/+ PyVT and Erbb2 tumors." (PMID 34283045, 2021). "HER2 was first functionally implicated in human breast cancer pathogenesis in 1987 when it was discovered that ERBB2 overexpression was a significant predictor of both overall survival (OS) and time to relapse." (PMID 33997928, 2021). "Consistent with our results, Hlavac and colleagues found that SLC46A1 variants are associated with ERBB2/HER2 status and disease-free survival in hormonally treated patients with breast carcinoma." (PMID 34055632, 2021). "The ERBB2 gene is mutated in 14.05% of breast carcinoma patients, with amplification present in 11.18%." (PMID 34259866, 2021). "To investigate the consequences of Usp22 loss in HER2-driven mammary carcinomas, we utilized a transgenic mouse model in which the gene encoding HER2 (Erbb2) was expressed under the mammary-specific MMTV promoter (MMTV-Erbb2)." (PMID 34007022, 2021). "Preoperative chemotherapy (neoadjuvant chemotherapy) is commonly given to patients with high-risk breast cancer, particularly triple-negative ERBB2 (formerly HER2)-positive, and locally advanced breast cancer." (PMID 33107920, 2020). "While PIK3CA alterations occur in 36% or more of breast cancer patients there are other relevant biomarkers to consider in these patients, including ERBB2, BRCA1, BRCA2, NTRK, and MSI (or mismatch repair deficiency)." (PMID 32976510, 2020).
breast cancer (continued). "Breast cancer is a heterogeneous disease with involvement of hormone receptors (estrogen (ER) and progesterone (PR)), human epidermal growth factor receptor 2 (HER2, encoded by ERBB2), Wnt signaling receptors and/or BRCA mutations." (PMID 33096815, 2020). "The neoadjuvant treatment options for ERBB2-positive (also known as HER2-positive) breast cancer are associated with different rates of pathologic complete response (pCR)." (PMID 33226431, 2020). "HER-2 positive breast cancer is caused by the amplification of the ERBB2/NEU receptor and associated with an increased risk of disease recurrence and death." (PMID 31895772, 2020). "Induction of ErbB2 degradation was proposed as an intriguing strategy to battle with ErbB2-positive breast cancer and reduced mutation-incurred drug resistance." (PMID 32327714, 2020). "ErbB2 overexpression identifies a subclass of breast cancer as ErbB2-positive that is frequently associated with poor prognosis." (PMID 32327714, 2020). "HOTAIR lncRNA is expressed in exosomes derived from breast cancer patients and is associated with ErbB2/HER2 positivity." (PMID 32337272, 2020). "Other clinical studies on RNA–RNA interactions underlying the mechanism of breast cancer identified upregulation of human receptor tyrosine-protein kinase erbB-2 (ERBB2) by BCLIN25 through regulation of promoter CpG methylation on miR-125ERBB2." (PMID 32326172, 2020). "Differential gene expression analyses by ERBB2 mutation and amplification status was performed using weighted average differences and an in silico model of response to neratinib derived from breast cancer cell lines." (PMID 32782013, 2020). "Studies have demonstrated that phosphorylated AKT is associated with ErbB2 overexpression and poor disease-free survival in breast cancer." (PMID 32499871, 2020). "In line with MEDICA effect in suppressing ErbB family members in transgenic ErbB2 breast cancer mice in vivo, loss of ErbB members and suppression of their respective transduction pathways were further verified in AU565 and BT474 human breast cancer cells." (PMID 32695336, 2020). "The overexpression of the ErbB-2 gene, which encodes HER2 oncoprotein exists in 20-25% of breast cancers, which is associated with poor prognosis, the higher chance of metastasis, and relapse." (PMID 32856881, 2020). "Our network analysis identified 11 protein complexes and signaling pathways that were significantly mutated, including the ERBB2 signaling pathway, the roles of which in breast cancer have been studied extensively." (PMID 33087126, 2020). "MacroH2A interaction with Her2 interaction leads to the activation of ERBB2, implicated in breast cancer metastasis." (PMID 32257110, 2020). "It is conceivable that this strategy will likely eliminate resistance incurred by ErbB2 mutations, as preceding investigations already revealed effectiveness of this approach against trastuzumab-resistant breast cancer." (PMID 32327714, 2020). "The study reported limited statistical evidence of a time-dependent effect of ERBB2 mutational status associated with short-term breast cancer-specific survival." (PMID 32782013, 2020). "Hundred percent of the mutations found in breast cancer were located in ERBB2 and similarly, BRAF accounts for all mutations in colorectal cancer and MAP2K1 in pancreatic cancers." (PMID 32757330, 2020). "ErbB2 amplification or overexpression is observed in ~25–30% of breast cancers and is associated with an aggressive clinical phenotype." (PMID 32366937, 2020). "LRIG1 copy number ratios were associated with the breast cancer subtype, steroid receptor status, ERBB2 status, tumor grade, and nodal status." (PMID 32448168, 2020). "The TK HER2 (human epidermal growth factor receptor 2, also known as ErbB2) is overexpressed in up to 25% of invasive or metastatic breast cancers, and is associated with an unfavorable prognosis." (PMID 32694997, 2020).
breast cancer (continued). "PIK3R1 is in a DriveWays module containing PIK3CA and ERBB2, both of which are associated with breast cancer through the CMbreast reference set." (PMID 33319839, 2020). "The most important risk factors for breast cancer outcome are tumor size, nodal involvement, tumor grade, ERBB2 status, proliferation index, and hormone receptor status." (PMID 32448168, 2020). "We found about 52.6% (20/38) of ERBB2 mutations were from breast cancer patients and 44.7% (17/38) were from lung cancer patients, with 59% of all mutations in β3‐αC loop were druggable." (PMID 32757330, 2020). "For example, in a mouse breast cancer model induced by polyoma middle T (PyMT) or ErbB2/Neu, loss of Akt1 significantly delayed tumor induction while loss of Akt2 accelerated this endpoint." (PMID 33110146, 2020). "Another approach to fight breast cancer is using redirected expanding NK-92 cells against the tumor-associated ErbB2 (HER2), a tissue antigen over-expressed in several human tumors, including breast, ovarian, stomach and prostate cancer." (PMID 32707982, 2020). "Human epidermal growth factor receptor 2 (HER2; ERBB2) is tyrosine kinase receptor and the mutation or amplification of which have been linked with human cancers, with lung cancer and breast cancer the most common." (PMID 32757330, 2020). "The Notch pathway is implicated in targeted treatment resistance in ErbB2/HER2 positive breast cancer, which is potentially attributed to the coregulation between Notch 1 and ErbB2/HER2 signalling." (PMID 32575680, 2020). "By applying correlative FM and STEM to single, QD-labeled ErbB2 proteins in actin-GFP transduced breast cancer cells; it was possible to detect distinct distribution patterns of membrane ErbB2 in dependency of the underlying actin content." (PMID 32714928, 2020). "Trastuzumab emtansine (T-DM1) is an antibody-drug conjugate, which is trastuzumab linked to the DM1 and was approved by the FDA for ERBB2-positive breast cancer patients with residual invasion." (PMID 32708604, 2020). "A homozygote or heterozygote loss of StarD13 in mammary tumors linked to ErbB2 (tyrosine phosphate -receptor), increased lung metastasis in vivo as well, further demonstrating StarD13 invasion and metastasis suppressor functions." (PMID 32900380, 2020). "Suppression of ErbB2 breast tumors by MEDICA in ErbB2/neu mouse transgenes as well as in human ErbB2 breast cancer cells was accompanied by loss of plasma membrane ErbB2, together with other ErbB family members, including EGFR (ErbB1) and ErbB3." (PMID 32695336, 2020). "This agent is used for the treatment of breast cancers that overexpress HER2/ErbB2 and is known to cause a reversible cardiomyopathy that is otherwise phenotypically similar to anthracycline-induced cardiomyopathy." (PMID 30755794, 2019). "Taken together, these data indicate that these two interacting proteins can associate to p140Cap in at least two different breast cancer subtypes (ERBB2-positive versus Luminal A subtypes)." (PMID 31681758, 2019). "In human breast cancer, ErbB3 interacts with ErbB2 and thereby generates a potent oncogenic dimer that causes tumor progression." (PMID 30621788, 2019). "Collectively, these results demonstrate that, in the context of ErbB2-driven breast cancer, c-Src loss reprograms bioenergetics and induces energy stress, reducing mTORC1 activity and thereby down-regulating the translation of PRC2 components." (PMID 31263101, 2019). "The primary role of DNAJC13 is in early endosome transportation, and in ERBB2 positive breast cancers has been implicated in the trafficking of epidermal growth factor receptor (EGFR) to the plasma membrane." (PMID 30578123, 2019).
breast cancer (continued). "In human epidermal growth factor receptor 2 (HER2/neu, c-erbB2) positive breast cancer cells, STARD3 is associated with a poor prognosis, and lower levels of STARD3 increase cell death while reducing cell proliferation." (PMID 30717356, 2019). "Clinically, high expression of both Grb7 and the ERBB family, especially ERBB2, are highly associated with a poor prognosis of patients with breast cancer." (PMID 31083325, 2019). "Previous studies have also suggested that ERBB2 overexpression is strongly associated with increased chemotherapy resistance leading to increase disease recurrence in breast cancers." (PMID 31448219, 2019). "Treatment with selected inhibitory compounds reduced the association of p130Cas to ErbB2 also in BT474 breast cancer cells." (PMID 30816273, 2019). "In patients with ERBB2-amplified breast cancer, a p140Cap-positive status associates with a significantly lower probability of developing a distant event, and a clear difference in survival." (PMID 31681758, 2019). "The HER2 (encoded by ERBB2) amplification group has achieved great clinical success because HER2 is an effective therapeutic target for breast cancer." (PMID 32039169, 2019). "In this diagnostic study of 209 patients, among HER2 (ERBB2)-positive breast cancers, an intratumoral and peritumoral imaging signature capable of discriminating the response-associated HER2-enriched molecular subtype was identified." (PMID 31002322, 2019). "NR1D1 is located in the ERBB2 amplicon region of chromosome 17q12–21 and is thought to be part of the ERBB2 signature, which is associated with poor clinical outcome in breast cancer." (PMID 31779659, 2019). "ERBB2, the target of the main mAbs used to treat breast cancer, is the gene most frequently reported as a biomarker of response in breast cancer, accounting for 59% of biomarkers with 23 different variants associated." (PMID 31169290, 2019). "ErbB2 overexpression identifies a subset of breast cancer as ErbB2-positive and is frequently associated with poor clinical outcomes." (PMID 30786890, 2019). "In a similar fashion, it has been described that the tyrosine kinase receptor ErbB2 translocates to the nucleus and physically associates with nuclear β-actin in breast cancer cells." (PMID 30643008, 2019). "A most well known disease associated with TOP2A is female breast cancer, it is usually deleted or amplified simultaneously with ERBB2, thus the two genes are commonly co-tested in breast cancer patients for further proper use of anticancer agent herceptin." (PMID 31528121, 2019). "HER2+ (erbB2) represent 25 to 30 % of breast cancer patients and is elevated expression has been associated with more aggressive BC phenotype and shorter DFS and OS21,22." (PMID 31263577, 2019). "Amplification of ErbB2 is found in about 20% of breast cancers and is classically associated with a poor prognosis." (PMID 29662626, 2018). "Overproduction of ErbB2 by the tumor cells is associated with a higher rate of disease recurrence and shorter overall survival than observed in other breast cancer types." (PMID 30545388, 2018). "Breast cancers with ERBB2 gene amplification were associated with a poor prognosis prior to the availability of HER2-targeted therapy." (PMID 30005627, 2018). "Hyperactivation of the PI3K/AKT/mTOR pathway is frequently observed in breast cancer and is often associated with resistance to both anti-ERBB2-targeted and endocrine therapies." (PMID 29515110, 2018). "The gene sequence of PBP and NR1D1 are located in the ERBB2 amplicon, and in breast cancer, mutations in this gene locus are linked to high lipid synthesis and PBD, NR1D1 overexpression." (PMID 29966227, 2018). "The membrane protein HER2 (also known as ErbB-2, Neu, CD340) is closely associated with malignancy, and is highly expressed in various tumors including mammary tumors." (PMID 29466990, 2018).
breast cancer (continued). "Of all variant classes, RET amplifications were the most commonly observed and mainly found in ER− and ERBB2− (ERBB2 wild-type/HER2-) breast cancers, followed by missense mutations and rearrangements." (PMID 30446652, 2018). "Overall, the primary breast cancer and the three synchronous and spatially distinct brain metastatic lesions, in addition to displaying a clonal ERBB2 (HER2) gene amplification, harbored 27 somatic mutations." (PMID 29755676, 2018). "A previous study reported association between NRF2 and HER-2 in the ErbB2/HER-2-positive breast cancer cell line BT-474, with knockdown of NRF2 leading to repression of HER-2 expression." (PMID 29682102, 2018). "The classical example of the role of large genomic rearrangements as oncogenic drivers is HER2+ breast cancer in which the ERBB2 gene (encoding the HER2 receptor subunit) is amplified along with several other genes in the vicinity of chromosome 17q12." (PMID 30005627, 2018). "In HER2+ breast cancer, ERBB2 is mutated and results in aberrant activation of RAS signalling that drives HER2+ breast cancer progression." (PMID 29497041, 2018). "Numerous reports have implicated t-DARPP in breast cancer patients acquiring resistance to trastuzumab (Herceptin), a monoclonal antibody targeting the ERBB2 (Her2/neu) receptor." (PMID 29782621, 2018). "Concerning ERBB2-mutated breast cancers, a phase II has reported a CBR of 31% in 22 patients treated with neratinib." (PMID 29515767, 2018). "We also showed that ErbB2-overexpressing breast cancer cells are more sensitive to ganetespib as compared to ErbB2-deficient parental breast cancer cells." (PMID 29717218, 2018). "Further, mutations in ERBB2 had been known as therapeutic targets in lung and breast cancer in vitro." (PMID 30018982, 2018). "RCAS-caErbB2 expresses a constitutively active form of rat ErbB2 (HER2/Neu); ErbB2 is amplified/mutated in 20–25% of human breast cancers." (PMID 29778097, 2018). "The receptor tyrosine kinase ErbB2 (HER2) is amplified in about 25% of human breast cancers and is associated with an aggressive phenotype and reduced response to hormone therapies." (PMID 30145750, 2018). "Certain RTK gene alterations, such as ERBB2 amplifications in breast cancer and EGFR mutations in lung cancer, are excellent therapeutic targets and used in clinical practice." (PMID 28099935, 2017). "In some cases like the TCGA BRCA copy number data, we found that copy number measurements were saturated for some highly amplified genes such as ERBB2, a gene encoding a receptor tyrosine kinase that is highly amplified in breast cancer." (PMID 29259170, 2017). "In contrast, a recent study reported that autophagy protein ATG4B has a positive association with ErbB2 in a subtype of breast cancer cells." (PMID 28338617, 2017). "Breast cancers with highly suspicious calcifications are associated with high levels of mRNA expression of ERBB2 and decreased immune system activity." (PMID 28900139, 2017). "Over-expression of the tyrosine kinase associated receptor HER2, and amplification of its gene ERBB2, is found in 15–23% of all breast cancers." (PMID 28509845, 2017). "Here we report that in patients with ERBB2-amplified breast cancer, a p140Cap-positive status associates with a significantly lower probability of developing a distant event, and a clear difference in survival." (PMID 28300085, 2017). "TFAP2A expression was found to be less organized in breast cancer compared to normal mammary gland and it is associated with HER2/ErbB-2 and ERα expression." (PMID 28412966, 2017). "ERBB2 is amplified and overexpressed in 20% to 30% of human breast cancers (BCs), and it is often associated with aggressive disease and poor prognosis." (PMID 29100552, 2017). "First, breast cancers with highly suspicious calcifications are associated with high levels of mRNA expression of ERBB2 and decreased expression of COL11A1 and FNDC1." (PMID 28900139, 2017).